CNGB3 (cyclic nucleotide gated channel subunit beta 3)
Diseases named in the same sentence as CNGB3 in open-access papers (continued):
Sharing a sentence is not in itself a finding about the gene and the disease.
achromatopsia (continued). "Day-blindness is a rather rare finding in canines with only CNGB3-achromatopsia having been thoroughly characterized." (PMID 23601474, 2013). "In the majority of patients, achromatopsia is a channelopathy and caused by mutations in either the CNGA3 or CNGB3 gene, with CNGB3 being affected most commonly." (PMID 23601474, 2013). "Except for a transgenic CNGB3-knockout mouse, the dogs discussed here represent the only known animal model of CNGB3-achromatopsia, the most common form of the disease in humans." (PMID 23601474, 2013). "Achromatopsia results from mutations in one of three genes: cyclic nucleotide-gated channel, alpha-3 (CNGA3); cyclic nucleotide-gated channel, beta-3 (CNGB3); and guanine nucleotide-binding protein, alpha-transducing activity polypeptide 2 (GNAT2)." (PMID 18636117, 2008). "Mutations in CNGA3, CNGB3, and GNAT2 have been associated with the majority of studied cases of achromatopsia." (PMID 18636117, 2008). "Mutations in CNGA3 and CNGB3 cause achromatopsia but do not show a consistent association with myopia." (PMID 40535564, 2025). "We established a three-dimensional protein structure-based proteoform analysis of the CNGA3/CNGB3 complex to better understand CNG channel-dependent achromatopsia pathology and determined the pathogenicity and potential disease pathology of our patient’s mutation." (PMID 40448196, 2025). "Myopia is a prominent feature of some of the disorders, including blue cone monochromacy, Bornholm eye disease, PDE6‐associated achromatopsia (but not achromatopsia associated with CNGA3 or CNGB3) and ARR3‐associated disease (in females)." (PMID 40013354, 2025). "Variants in the CNGB3 gene are responsible for approximately 50% of all patients with achromatopsia and not iMD, which complicates this analysis." (PMID 38540785, 2024). "Achromatopsia is caused by sequence variants in CNGA3, CNGB3, GNAT2, PDE6H, PDE6C, and ATF6." (PMID 39273686, 2024). "However, several trials target the CNGA3 and CNGB3 gene mutations in another IRD, achromatopsia (ACHM) (NCT03278873, NCT02610582)." (PMID 37763275, 2023). "Achromatopsia (OMIM:216,900), also called rod monochromatism, characterized by dysfunction of the cone photoreceptors was observed in 3 consanguineous families displaying mutations in CNGA3, CNGB3 and GNAT2, respectively." (PMID 35551639, 2022). "Of 19 diseases, 10 had >10 participants: ABCA4 retinopathy; CNGB3- and CNGA3-associated achromatopsia; RPGR-associated disease; RPE65-associated disease; blue cone monochromacy (BCM); Bornholm eye disease (BED); TYR- and OCA2-associated oculocutaneous albinism; and GPR143-associated ocular albinism." (PMID 35704304, 2022). "In summary, although CNGA3—together with CNGB3—contributes the major parts of the CNG protein channel, where many achromatopsia patients carry mutations in both genes, merely having a small amount of normal CNGA3 protein is sufficient to form “functional” CNG channels." (PMID 34360834, 2021). "However, constitutive synthesis of cGMP at the inner segment compartment of cones has been shown to be very toxic and the basis of the physiopathology in mouse models of achromatopsia caused by null mutations in cone CNG-channel subunits CNGA3 and CNGB3." (PMID 31980596, 2020). "Because loss-of-function of CNGB3 causes achromatopsia and there was no disease phenotype in both CNGB3+/+ and CNGB3+/− mice, we inferred that the decrease in CNGB3 resulted from successful biallelic deletion of CNGB3 in two of three cones in cone_6." (PMID 32953936, 2020). "The product of CNGB3 provides instructions for making the β-subunit of the cone photoreceptor cyclic nucleotide-gated (CNG) channel, but mutations lead to a defective photoreceptor, decreased visual acuity, and total color blindness, or achromatopsia." (PMID 31069169, 2019).
achromatopsia (continued). "Variants found in both genes (USH2A and CNGB3) segregated in the family; therefore suggesting a RP diagnosis due to USH2A, and a likely cone dystrophy/achromatopsia diagnosis due to CNGB3 in the proband; and a cone dystrophy/achromatopsia diagnosis in his brother (sibling II:2)." (PMID 29912909, 2018). "Mutations associated with the CNGB3 subunit are most common in European subjects (ACHM3; OMIM# 262300) and account for 50% of all known cases worldwide, whereas the CNGA3-associated achromatopsia (ACHM2; OMIM# 216900) accounts for ~30% of all diagnosed cases thus far." (PMID 26407004, 2015). "We also reported the occurrence of CNGB3-deletion-achromatopsia in a new canine breed, the MAS." (PMID 23601474, 2013). "CNGB3-achromatopsia is the most common form of achromatopsia in humans." (PMID 23601474, 2013). "Specifically, we detected pathogenic DNA variants (∼50% novel mutations) in the genes RP1, USH2A, CNGB3, NMNAT1, CHM, and ABCA4, responsible for retinitis pigmentosa, Usher syndrome, achromatopsia, Leber congenital amaurosis, choroideremia, or recessive Stargardt/cone-rod dystrophy cases." (PMID 23940504, 2013). "We report the occurrence of CNGB3-achromatopsia in a new canine breed, the MAS." (PMID 23601474, 2013). "Thus, AAV8-hCARp.h CNGB3 gene therapy is a promising approach for the treatment of achromatopsia." (PMID 40002778, 2025). "To determine whether PR dysfunction without ongoing degeneration also induces PRLΔE1 expression, we examined a model of achromatopsia (CNGB3-ACHM3; mutation in Cyclic Nucleotide Gated Channel Subunit Beta 3), a disease with impaired cone function and structure, but no rod degeneration." (PMID 39294136, 2024). "For example, investigations into the cause of the high prevalence of achromatopsia in the population residing on the atoll of Pingelap in Micronesia (about 5%) resulted in the identification of the causative mutation (in a locus named ACHM3) and the identification of the cone specific CNGB3." (PMID 36584110, 2022). "The similar clinical presentation between familial achromatopsia in humans and bovine recessive day-blindness led to the hypothesis that a protein-changing variant within CNGA3, CNGB3, GNAT2, ATF6, PDE6C, and PDE6H would be associated with achromatopsia of Original Braunvieh calves." (PMID 34830323, 2021). "Genetic defects in CNGA3 and CNGB3, encoding two structurally related subunits of cone CNG channels, lead to achromatopsia (ACHM)." (PMID 26407004, 2015). "Preliminary safety and efficacy of AGTC-401 and AGTC-402 in CNGB3- and CNGA3-related achromatopsia were presented at ARVO." (PMID 39273686, 2024). "In a study aimed at evaluating the safety of AAV carrying CNGB3 for the treatment of achromatopsia, three groups of NHPs received a subretinal injection with either a vehicle or AAV-CNGB3 at a low or high dose." (PMID 36145721, 2022). "As a result of these successes in various animal models, phase I/II human clinical trials are in progress for CNGB3 (NCT02599922) and CNGA3 (NCT02610582) achromatopsia using AAV-mediated delivery of these genes." (PMID 30667376, 2019). "We also report the occurrence of achromatopsia in a MAS based on the identical classical clinical phenotype and genomic CNGB3 deletion that was reported in the AM." (PMID 23601474, 2013). "Jin and colleagues delivered AAV-mediated CRISPR-cas9 targeting a cone-specific gene, CNGB3, to rapidly generate a non-human primate model with achromatopsia." (PMID 32953936, 2020). "No efficacy was evident in CNGB3-achromatopsia patients, and only moderate efficacy was observed in RP patients and patients with geographic atrophy secondary to dry AMD." (PMID 32629980, 2020). "Mutations in CNGA3 (MIM#600053), CNGB3 (MIM#605080), GNAT2 (MIM#139340), and PDE6C (MIM#600827) have been detected in four probands with OT, which all encode cone phototransduction pathway proteins, suggesting a pathomechanistic overlap with achromatopsia (ACHM)." (PMID 28829391, 2017).
achromatopsia (continued). "Treatment for achromatopsia was successful in CNGA3-KO and CNGB3-KO mice." (PMID 25650393, 2015). "The genotypes were compared between a purebred, cd-affected AM and three AMs not affected with CNGB3-deletion-achromatopsia (one of the three unaffected AMs was an obligated carrier, the parent of the affected dog)." (PMID 23601474, 2013). "Based on eye certification data and our DNA testing results over the past 20 years, we suspect that CNGB3-achromatopsia has become rare or even non-existent in North American AMs, but it is still reported in Australia." (PMID 23601474, 2013). "CNGA3_R410W/CNGB3 and TAX4_R421W channels are spontaneously active without cGMP and induce cell death, suggesting cone degeneration triggered by spontaneous CNG channel activity as a possible cause of achromatopsia." (PMID 35233102, 2022). "The low proportion of patients with FAF Groups 3 and 4, and OCT Grades 3 and 4 in our study, can support the speculation that those stages are short transitional state of the disease natural history, in contrast to CNGB3-, CNGA3-, and PDE6C-achromatopsia where Grade 4 is more common." (PMID 33737031, 2021). "However, our cone ERGabsentRPGRIP1ins/ins animal retains sufficient photopic vision, suggesting that the observed reduction in CNGB3 is a secondary effect of the diseased cones, rather than a primary defect as in CNGB3-achromatopsia." (PMID 28993665, 2017). "Importantly, as the full-field ERG was the distinguishing feature between LCA and achromatopsia that is related to CNGB3, the early assessment of patients with full-field ERG will potentially identify the frequency of the LCA phenotype in CNGB3 related retinal dystrophy." (PMID 29186038, 2017).
myopia (9 papers, 2018 to 2025). "Hyperopia and myopia were equally frequent among patients presenting CNGA3 mutations (50% and 50%, respectively), while myopia was more frequent than hyperopia among subjects with CNGB3 mutations (86% versus 14%)." (PMID 29618791, 2018). "RP2 and CNGB3 are expressed in cones and rods and are associated with syndromic myopia." (PMID 36418970, 2022).
cone dystrophy (7 papers, 2010 to 2023). An inherited ocular disorder characterized by the loss of cone cells, the photoreceptors responsible for both central and color vision. "Mutations in CNGA3, CNGB3, and PDE6C have also been associated with cone dystrophy in a small proportion of patients." (PMID 20454696, 2010). "The CNGB3 gene, which has also previously been shown to be involved in ACHM and cone dystrophy, resides in one of these regions on chromosome 8q21.3." (PMID 20454696, 2010).
Retinal dystrophy (5 papers, 2017 to 2024). Retinal dystrophy is an abnormality of the retina associated with a hereditary process. "Mutations in CNGB3 can lead to various forms of retinal dystrophy, adversely affecting the function and survival of cone photoreceptors." (PMID 39595990, 2024). "Many gene mutations in ocular ion channels were reported (e.g., CACAN1A, CACNG8, CNGB3) to contribute to retinal dystrophy." (PMID 36431052, 2022).
macular degeneration (4 papers, 2013 to 2024). Loss of vision in the central portion of the retina (macula), secondary to retinal degeneration. "Mutations in CNGB3 have been linked to a number of disorders, including color blindness and macular degeneration in teenagers." (PMID 38880869, 2024). "Four of 12 nsSNP-phenotype associations were successfully replicated in an independent data set: thrombosis (F5,rs6031), seizures/convulsions (GPR98,rs13157270), macular degeneration (CNGB3,rs3735972), and GI bleeding (HGFAC,rs16844401)." (PMID 24949630, 2014).
retinal disease (4 papers, 2014 to 2025). "Variants in the CNGB3 gene, encoding the B3‐subunit of the cone photoreceptor cyclic nucleotide gated channel, are a major cause of autosomal recessive achromatopsia, a rare inherited retinal disease." (PMID 40304364, 2025). "In family RP-0605, re-analysis with NGS uncovered the presence of two coexisting retinal diseases (RP and cone affectation), since biallelic pathogenic variants in two different RD-related genes (USH2A and CNGB3) have been identified." (PMID 29912909, 2018). "Because the affected dogs did not share common alleles, we excluded single, fully penetrant mutations in six known canine retinal disease genes: BEST1, PDE6B and PDE6A, RPE65, NPHP4, and CNGB3." (PMID 25198798, 2014).
retinitis pigmentosa (4 papers, 2013 to 2025). Retinitis pigmentosa (RP) is an inherited retinal dystrophy leading to progressive loss of the photoreceptors and retinal pigment epithelium and resulting in blindness usually after several decades. "The resulting dendrogram captures some of the known phenotypic similarities in IRDs such as Stargardt phenocopy genes (ABCA4, PRHP2 and PROM1), retinitis pigmentosa genes (RPGR and USH2A) and achromatopsia genes (CNGA3 and CNGB3)." (PMID 40567353, 2025).
cone-rod dystrophy (3 papers, 2008 to 2024). Inherited retinal dystrophies that belong to the group of pigmentary retinopathies. "The genes involved in cone degeneration, CNGB3, CNGA3 and GNAT2, and the genes involved in cone-rod dystrophy, ABCA4, RDH5, Cord8, Cord9, RPGRIP1, GUCY2D and CRX, were all excluded from being involved in the cone-rod dystrophy described in this family of SWHD." (PMID 18593457, 2008). "Three of the genes, CNGB3, CNGA3 and GNAT2, involved in cone degeneration and seven genes and loci, ABCA4, RDH5, CORD8, CORD9, RPGRIP1, GUCY2D and CRX, reported to be involved in cone-rod dystrophies were studied." (PMID 18593457, 2008).
Blindness (2 papers, 2014 to 2021). Blindness is the condition of lacking visual perception defined as a profound reduction in visual perception. "We propose that the D262N mutation in dogs with CNGB3-day blindness results in the loss of these inter-helical interactions altering the electrostatic equilibrium within in the S1–S4 bundle." (PMID 24586388, 2014). "An aspartatic acid (Asp) to asparagine (Asn) missense mutation at position 262 in the canine CNGB3 (D262N) subunit results in loss of cone function (daylight blindness), suggesting an important role for this aspartic acid residue in channel biogenesis and/or function." (PMID 24586388, 2014).
gastric cancer (2 papers, 2023 to 2024). A primary or metastatic malignant neoplasm involving the stomach. "The four nucleotide metabolism-related genes that make up NMRI (GAMT, ORC1, CNGB3, and SERPINE1) were verified in an external dataset and are a valid predictor of prognosis for patients with gastric cancer." (PMID 38880869, 2024). "The expression of GAMT was considerably down-regulated in gastric cancer tissues when compared to normal gastric tissues, while the expression of ORC1, CNGB3, and SERPINE1 was significantly up-regulated in gastric cancer tissues." (PMID 38880869, 2024). "The mRNA levels of RAI14, GUCY1A2, CNGB3, FJX1, FZD2, ELOVL2, and GDPD4 were all expressed upregulated in gastric cancer tissues, except for CXCL13, whose expression level was not significantly different between gastric cancer tissues and normal cell lines." (PMID 36823639, 2023).
juvenile macular degeneration (2 papers, 2014 to 2017). "Variants in CNGB3 have been associated with achromatoplasia and juvenile macular degeneration." (PMID 24949630, 2014).
endometriosis (1 paper, 2014). The growth of functional endometrial tissue in anatomic sites outside the uterine body. "We tested the effect of a mixture of dKLAK-z13 and HLAH-z13 peptides on baboon endometriosis models in vivo, as baboon endometriosis tissues were stained by anti-CNGB3 antibody in a similar manner as human endometriosis lesions are stained." (PMID 25047118, 2014). "To examine CNGB3 protein expression in endometriosis, we generated a mouse monoclonal antibody against a peptide sequence of human CNGB3, corresponding to K721 to P750 within the cytoplasmic domain." (PMID 25047118, 2014). "We also identified its receptor as the cyclic nucleotide-gated channel β3 (CNGB3) and confirmed its expression in endometriosis." (PMID 25047118, 2014).
retinal degeneration (1 paper, 2021). Degeneration of the retina. "A cross-sectional analysis of the largest patient cohort to date suggests that biallelic variants in CNGA3 and CNGB3 in most patients result in slow retinal degeneration that occurs over decades of life." (PMID 34449556, 2021).
retinopathy (3 papers, 2021 to 2023). "An accessory CNGA3 variant with the two CNGB3 variants, one being c.1208G > A;p.(R403Q), was recently described as exacerbating CNG-channel retinopathy." (PMID 36980963, 2023). "The cross-sectional analysis showed evidence that CNGA3/CNGB3 retinopathy is a progressive disease that follows four OCT stages; (I) preserved ISe, (II) disrupted ISe, (III) ISe loss, and (IV) ISe, and RPE loss, which occur slowly over decades." (PMID 34449556, 2021). "Animal models support the proposed degenerative nature of CNGA3/CNGB3 retinopathy." (PMID 34449556, 2021).
cardiovascular disease (1 paper, 2021). "For PRKAR1A, SI and CNGB3 no relevant associations with cardiovascular disease were identified, except for a relatively weak association between CNGB3 and varicosity." (PMID 34169069, 2021). "Overall, 86 genes were identified to significantly modify the cardiovascular disease severity in PXE, of which four genes are present in both tests (HCAR3, CNGB3, SI, and PRKAR1A)." (PMID 34169069, 2021).
CNGB3 also shares sentences with these, for which no sentence is quoted: Leber congenital amaurosis (4 papers); Nystagmus (3); channelopathies (2); geographic atrophy (2); Hypermetropia (2); Stargardt disease (2); achromatopsia 3 (1); blue cone monochromacy (1); cd (1); Chorioretinal atrophy (1); choroideremia (1); convulsion (1); glaucoma (1); Intellectual disability (1); Leber congenital amaurosis 2 (1); macular telangiectasia type 2 (1); occult macular dystrophy (1); ocular albinism (1); oculocutaneous albinism (1); Photophobia (1); Stroke (1); thrombosis (1); tumor (1); Usher syndrome (1).